XKRX (XK related X-linked)
Synonyms: XKR2; XPLAC; XRG2
Tractability: Antibody: UniProt places it where antibodies can reach, with high confidence; UniProt predicts a signal peptide or a membrane-spanning region; its Gene Ontology location is reachable by antibodies, with medium confidence.
Gene: Protein-coding gene on chromosome X (100,913,445 to 100,929,433, reverse strand). Ensembl gene ENSG00000182489.
Subcellular location: Cell membrane
Gene Ontology:
Cellular component: membrane; plasma membrane
Homologues: Orthologues: chimpanzee XKRX (100% identical), macaque XKRX (98% identical), dog XKRX (94% identical), pig XKRX (94% identical), rat Xkrx (92% identical), guinea pig XKRX (92% identical), mouse Xkrx (92% identical), rabbit XKRX (92% identical), tropical clawed frog xkrx (48% identical), zebrafish xkrx (44% identical). Paralogues in human: XKR3 (47% identical), XK (40% identical).
Diseases named in the same sentence as XKRX in open-access papers:
XKRX is named in the same sentence as 1 disease in open-access papers, as found by Europe PMC text mining. Sharing a sentence is not in itself a finding about the gene and the disease.
XKRX shares sentences with these, for which no sentence is quoted: colon cancer (1 paper).